HIF1A (hypoxia inducible factor 1 subunit alpha)
Diseases named in the same sentence as HIF1A in open-access papers (continued):
Sharing a sentence is not in itself a finding about the gene and the disease.
tumor (continued). "However, HIF-1α-positive areas were substantially expanded over the pimonidazole-positive hypoxic areas in NQO1-overexpressing tumours (RKO/pNQO1)." (PMID 27966538, 2016). "Since HO-1 may be associated with the expression of HIF-1α and VEGF, we hypothesized that HO-1 inhibitor ZnPP was able to obstruct tumor growth and spread of cancer cells by inhibiting the HO-1-induced HIF-1α expression coupled with VEGF-mediated angiogenesis." (PMID 26822586, 2016). "Interestingly, overexpressing a degradation-resistant mutant of HIF1α or abolishing the HIF1α-degrading machinery promotes anti-tumor responses in T cells, including cytotoxic activity and production of IFNγ." (PMID 26885366, 2016). "Many studies strongly support that HIF1α functions as a tumor-promoting gene." (PMID 26743088, 2016). "Pre- and post-TAE tumor biopsy specimens along with post-TAE whole liver tumor sections were stained with an HIF-1α antibody and analyzed to determine the percentage of HIF-1α positive nuclei using a spectral unmixing system mounted on a high-powered microscope." (PMID 26985249, 2016). "However, TR-764 showed the ability to induce the delocalization of the transcription factor HIF-1α from the nucleus to the cytoplasm in a xenograft murine model, thus triggering its inactivation and counteracting this character of tumor malignancy." (PMID 27292568, 2016). "The oncogenic miR-21, miR-337, miR-543, miR-214 and miR-130 are known to induce tumour-associated neovascularisation by directly targeting PTEN and activating PI3K/AKT, as well the ERK1/2 signaling pathways, which increases HIF1α and vascular endothelial growth factor (VEGF) expression." (PMID 27213336, 2016). "Currently, HIF-1α has been widely used in the evaluation of tumor in anaerobic conditions." (PMID 26853843, 2016). "HIF-1α/2α are the key regulators of the tumor cell response to hypoxia." (PMID 27741516, 2016). "Indeed, culture of PC3 cells under hypoxic (1% oxygen) conditions or treatment with HIF-1α inducer CoCl2 efficiently increase the expression of glycolytic genes to levels comparable to those observed in tumor cell-adipocyte co-cultures." (PMID 27588494, 2016). "In addition, other studies also indicate that HO-1 can trigger and regulate HIF-1α expression in hypoxic tumor cells." (PMID 26822586, 2016). "To determine whether this hypoxic signature was necessary for DTC tumor growth, we silenced HIF-1α in DTC by lentiviral vectors expressing HIF-1α-specific short hairpin (sh) RNA and monitored their growth in the s.c. pocket of NSG mice." (PMID 27105499, 2016). "Our finding suggested that the miR-101/VHL/HIF1α axis may play a tumor suppressive role when adequate oxygen was supplied to the tumor." (PMID 26841847, 2016). "HIF-1α and VEGF association with Axl, ALDH1, and c-KIT markers of tumor angiogenesis." (PMID 26760782, 2016). "HIF1α controls the expression of many genes, some of which may have opposite impact on tumour growth than PDHK1." (PMID 27498883, 2016). "Moreover, β-catenin can interplay with Snail and other metastasis-related factors, for example, Hif-1α, Forkhead box 3a, and Forkhead box 4, suggesting that β-catenin complexes play vital roles in tumor dissemination and metastasis." (PMID 26734994, 2016). "It is a subject of active investigation how HIF1α affects memory formation and anti-tumor immunity." (PMID 27510264, 2016). "We found that HIF-1α was present in the cytoplasm of T-cell leukaemia Jurkat cells and was subjected to DAPK regulation, suggesting that DAPK likely exhibits a tumour suppressor effect in T leukaemia cells by directly binding to the cytosolic HIF-1α to prompt HIF-1α downregulation." (PMID 27312851, 2016). "Interestingly, the density of HIF1α- and HIF2α-positive cells revealed higher expression of HIF2α compared to HIF1α in both the regions, suggesting different roles for these factors in the regulation of tumor development, as discussed in the next sections." (PMID 27705944, 2016).
tumor (continued). "To discern whether this hypoxic signature was imposed by the microenvironment or it was dependent on intrinsic features of tumor cells, we next investigated HIF-1α levels in the cells isolated from DTC tumors." (PMID 27105499, 2016). "Therefore, our results reveal for the first time that 14-3-3ζ functions as a positive regulator of HIF-1α, and the induction of HIF-1α by 14-3-3ζ augments the metastatic potential of tumor cells under hypoxic conditions." (PMID 26910835, 2016). "Herein, we showed that Salmonella had the ability to reduce HIF-1α expression and may improve the hypoxic condition in the tumor microenvironment as well as increase the effects of radiation or chemotherapy." (PMID 27175584, 2016). "Angiogenesis is activated by the HIF-1α/VEGF pathway in hypoxic tumor microenvironments." (PMID 27285755, 2016). "The importance of cofactors that regulate HIF-1α signalling within tumor is not well understood." (PMID 26909598, 2016). "Based on the results herein, it is evident that there are many shared traits among ccRCC stages related to the Warburg effect, but it seems likely that there are major differences between tumor stage related to the VHL/HIF1A/HIF2A axis that likely affect tumor aggressiveness and treatment." (PMID 27128972, 2016). "For instance, HIF-1α is a central regulator of Hsp90α secretion in both normal and tumour cells." (PMID 26846992, 2016). "In addition to an induced expression by the hypoxic tumor microenvironment, the precise mechanism of an increased constitutive expression of HIF-1α is still elusive." (PMID 26872370, 2016). "Despite these discrepancies there is clear evidence of associations between prognosis and poor tumor oxygenation biomarkers such as HIF-1α, GLUT-1 and lactate, though these associations are not exclusive." (PMID 27434126, 2016). "Moreover, high ROS production in cancer cells can stabilize survival factors such as HIF1α, which drive tumor initiation and progression." (PMID 27455839, 2016). "After treatment with rhES-AuNPs-PEG, HIF-1α expression was significantly reduced in the tumours." (PMID 27470938, 2016). "Importantly, survival was decreased in mice bearing orthotopic R132H IDH1 GBM tumours expressing the constitutively active HIF1α (CA-HIF) compared with vector-only tumours." (PMID 27820599, 2016). "Taken together, we conclude that ZFP91 promotes the tumor growth through HIF-1α in vivo." (PMID 27144516, 2016). "HIF-1α involves two aspects in tumor invasion and metastasis." (PMID 26958938, 2016). "The results above prompted us to examine the effect of the HIF-1α-GAPLINC axis on tumor growth." (PMID 27729869, 2016). "Importantly, we demonstrate that DEK promotes tumor angiogenesis and growth in HIF-1α-dependent and -independent manners." (PMID 26988756, 2016). "As a first step, we tested the effect of myeloid-specific HIF-1α knockout on tumor growth." (PMID 27834402, 2016). "However, it remains poorly understood about the role of miRNAs in HIF-1α-altered tumor cell metabolism." (PMID 27153552, 2016). "One of the main regulators of cell transformation and cancer progression is HIF‐1α, which not only plays an essential role in hypoxic tumors, but also regulates a large variety of target genes controlling the malignancy of several tumor types, which express HIF‐1α even in normoxic condition." (PMID 27138568, 2016). "In contrast, under hypoxia environment, the degradation process is suppressed and HIF-1α translocates from the cell plasma to the nucleus, where it could regulate the expression of more than 60 genes involved in crucial aspects of tumor biology." (PMID 27606158, 2016). "Currently, research on the level of HIF-1α of tumor patients is reported less." (PMID 26853843, 2016).
tumor (continued). "Our findings support a model in which the induction of the EMT regulator ZEB2 by hypoxia and HIF-1α allows tumour cells to flexibly respond to microenvironmental cues and repress repulsive signals such as ephrinB2, enabling cells to diffusely invade the surrounding parenchyma." (PMID 27470974, 2016). "In addition, several inflammatory cytokines, including TNF-α, IL-1, IL-6, TGF-β and IL-18, have been documented to increase HIF-1α expression or transcriptional activation in tumor cells." (PMID 26910835, 2016). "The distributions of HIF-2α+ cells and SOX2+ HIF-1α+ RNApII-S2P-/low cells overlapped only occasionally in the areas around large ischemic necroses, and the overall distribution patterns of these 2 subpopulations of tumor cells were essentially different." (PMID 26799577, 2016). "The expression of HIF-1α was decreased in Salmonella-treated tumor cells (B16F10 and 4T1)." (PMID 27175584, 2016). "Hence, ectopically expressing methylation-defective HIF-1α K32A MT provides cells with tumour growth advantage." (PMID 26757928, 2016). "The HIF-1α-mediated hypoxia-dependent down-regulation of E-cadherin and upregulation of N-cadherin is caused by the activation of the transcription factor SNAI2 thereby promoting EMT of tumor cells." (PMID 27044404, 2016). "Targeting the HIF-1a/VEGF-A axis may be a promising strategy for combating tumor recurrences following hyperthermia treatment." (PMID 27456341, 2016). "In tumor hypoxia, HIF-1α is an important regulator of the angiogenesis." (PMID 26784107, 2016). "Additionally, the anti-tumoral effect was associated with a reduction of tumor hemoglobin content, vascular density and inhibition of VEGF and HIF-1α expression." (PMID 27286448, 2016). "Notably, HIF1α has been identified as an important mediator of EMT in tumor cells via activation of Twist, Snail, and SIP1." (PMID 26856989, 2016). "HIF-1α has been reported to be involved in tumor migration and invasion by regulating EMT." (PMID 26958938, 2016). "Finally, because PERK is, next to hypoxia, able to stimulate tumour growth, the normalisation of tumoural oxygen levels by PlGF inhibition is able to dually target pro-survival signalling via reduced activation of the HIF-1α and PERK pathway." (PMID 26753564, 2016). "Under the hypoxia environment, HIF-1α is activated in tumor cell, thus regulating the expression of hundreds of downstream target genes, thus promoting the activation of a large amount of protein factors, which participate in both tumor neovascularization and metastasis." (PMID 26853843, 2016). "However, as tumor size decreased, the oxygen supply became abundant within the tumor region, and this in turn reduced the expression of HIF-1α." (PMID 27602954, 2016). "In the present study, by combining clinical sample analyses with in vitro experiments, we characterized a niche harboring quiescent stem-like tumor cells of the SOX2+ HIF-1α+ RNApII-S2P-/low or NANOG+ HIF-1α+ RNApII-S2P-/low phenotypes, which are associated with an enhanced tumorigenic capacity." (PMID 26799577, 2016). "This evidence strongly suggests that p62 regulates the tumor-promoting ability of HIF1α." (PMID 26743088, 2016). "In addition, it has been shown that HIF-1α functions as a tumour suppressor in the context of kidney cancer." (PMID 26757928, 2016). "Directly targets HIF-1α and other miRNAs, enhancing tumor angiogenesis." (PMID 27551267, 2016). "Another study confirmed that HIF-1α could independently increase the malignant potential of a hypoxia-tolerant tumor cell line." (PMID 26812886, 2016). "An alteration in the levels of Sp1 and Sp3 could link MAOB and HiF-1α levels to tumor grade and aggressiveness." (PMID 26689994, 2016).
tumor (continued). "Current thinking suggests that HIF-1α acts as a tumour suppressor, slowing growth of ccRCC cells." (PMID 27358011, 2016). "Similarly, the blocking of HIF-1α related functions within the tumour microenvironment using innovative molecular therapies means new combinatorial approaches can be adopted, incorporating existing chemo- and radiotherapy regimens." (PMID 27416726, 2016). "All of the PAM PI3K, mTOR, or PI3K/mTOR inhibitors listed in the previous section may be viable methods of suppressing tumor acidosis by lowering HIF-1α levels." (PMID 26962408, 2016). "Overexpression of HIF-1α correlates with an advanced tumor stage and poor survival." (PMID 27551323, 2016). "The relationship between the plasma level of HIF-1α and the clinical features (age, sex, histological type, tumor differentiation grade, T stage, local lymph node status, pTNM stage, tumor size and smoking condition) of patient with NSCLC was analyzed respectively." (PMID 26853843, 2016). "HIF-1A activates survival pathways in tumor cells and increases production of angiogenic growth factors such as VEGF or fibroblast growth factor (FGF) and others, thereby inducing more aggressive tumor growth, influencing endothelial cell behavior, and promoting therapy resistance." (PMID 26956051, 2016). "Our data showing that LSD1 overexpression in cancer stabilizes HIF-1α and facilitates tumour angiogenesis may explain better how LSD1 promotes not only hormone-dependent cancers but also other types of cancer." (PMID 26757928, 2016). "Additionally, HIF-1α activation up regulates vascular epithelial growth factor (VEGF) expression, which manifests as the angiogenic hallmark in tumor biology." (PMID 26962408, 2016). "Indeed, conditional genetic depletion of myeloid-specific HIF-1α results in decreased VM network formation, dye perfusion and tumor size." (PMID 27834402, 2016). "The enhanced invasiveness of HIF-1α-induced tumor cells has been demonstrated in vitro." (PMID 26812886, 2016). "Thus there is an emergent need to find new strategies to overcome tumor resistance, and in particular to target HIF-1α that is overactivated in hypoxic condition." (PMID 27292568, 2016). "Interestingly, the level of HIF-2α in tumor tissues was found to be significantly lower than in peritumoral tissues, while the level of HIF-1α showed the opposite result, higher in tumor tissues than in paracancerous tissues." (PMID 27119229, 2016). "Furthermore, in order to assess vascular functionality, we evaluated gene expression of hypoxia-related genes HIF1a and HIF2a, and tumor hypoxia by the Hypoxyprobe assay." (PMID 27120788, 2016). "A bioinformatics analysis revealed a strong correlation between TNC mRNA upregulation and expression of hypoxia-induced genes in both WT and R132H IDH1 patient GBMs, and expression of carbonic anhydrase 9 (CA9), a HIF1α-target gene, was reduced in R132H tumours." (PMID 27820599, 2016). "Several studies have demonstrated that HIF-1α may predict tumor diagnosis and recurrence and monitor tumor invasion and metastasis." (PMID 26958938, 2016). "Thus, to elucidate the underlying molecular mechanism of enhanced stability of HIF-1 α, we measured acetylated HIF-1α in tumor cells exogenously expressing 14-3-3ζ." (PMID 26910835, 2016). "From a molecular point of view, two transcription factors, namely, HIF1α and NFκB, may be considered as master regulators of tumor cell adaptation to ROS." (PMID 26798421, 2016). "Here we used a combination of primary PDAC tissue specimens, patient-derived cancer associated fibroblasts (CAFs), and extensive metabolomics analyses to delineate the metabolic features of PDAC stroma and symbiotic effects on the tumor compartment mediated by HIF1α and MCT4." (PMID 27623078, 2016). "In contrast to minor effects in the oncogene-driven cancer model the loss of Hif-1α in myeloid cells almost completely attenuated tumor development in the chemical MCA-carcinogen driven model." (PMID 27015123, 2016).
tumor (continued). "HIF1A network was also activated, suggesting an adaptation to the hypoxic tumour environment." (PMID 27049916, 2016). "Moreover, the DKG-induced overall metabolic phenotype is consistent with previous reports on the role of HIF-1α in tumor expansion." (PMID 27058900, 2016). "Lactate contributes to macrophage polarization by stabilizing HIF-1α and inducing expression of typical M2-phenotype markers like VEGF and arginase-I (ARG-I), so that tumor-associated macrophages (TAMs) sense the metabolic changes in tumor cells and respond to them in a proangiogenic manner." (PMID 26997761, 2016). "We hypothesize that ZnPP may modulate HIF-1α through inhibiting HO-1, and then inhibit angiogenesis and tumor progression." (PMID 26822586, 2016). "Hypoxia-inducible factor-1 (HIF-1)α plays a significant role in tumor angiogenesis." (PMID 27175584, 2016). "Certainly MLT may affect important relationships between metabolomics and neoplasms through multiple mechanisms such as a downregulation of hypoxia inducible factor HIF-1α, a fact now documented for a long time and through independent studies." (PMID 26959015, 2016). "Our previous research has showed that ROS could activate Akt33 and up-regulate glycolysis by stabilizing Hif1α, and improve a tumor’s hypoxia tolerance." (PMID 26956544, 2016). "They modulate tumor growth by inhibiting HIF-1α expression in cancer models." (PMID 27551267, 2016). "The presence of tumor hypoxia induces stabilization of hypoxia-inducible factor 1 alpha (HIF-1α), which leads not only to induction of angiogenesis, but also upregulation of glycolytic metabolism, to maintain the ATP production necessary for cell survival and proliferation." (PMID 27331625, 2016). "Hypoxia-inducible factor-1α (HIF-1α) could make the tumor produce adaptive biological response to hypoxia and become more aggressive." (PMID 26853843, 2016). "Interestingly, in contrast to many other tumor types, HIF-1α and HIF-2α have opposing effects in ccRCC biology, with HIF-1α acting as a tumor suppressor and HIF-2α acting as an oncogene." (PMID 27322325, 2016). "Importantly, HIF-1α has been demonstrated to regulate cellular metabolism in cancer cells making it a prime candidate to study as an inhibitor of increased tumor metabolism." (PMID 26962408, 2016). "Control RKO tumours exhibited clear correlative HIF-1α expression along hypoxic areas." (PMID 27966538, 2016). "However, the activation of HIF1α by ROS in sublethally damaged tumor cells closer to the vessels allows the expression of HIF1α-driven genes that contribute to their survival and growth thereby increasing their commitment to malignancy." (PMID 26798421, 2016). "In addition, there was a negative correlation (r=−0.51; Spearman's rank correlation coefficient) for HIF-1α and phospho-mTOR S2448 expression in pT1M0 tumours." (PMID 27291893, 2016). "Moreover, knock down of HIF-1α in HCT-116 tumor xenografts prevented VM and reduced gene expression changes implicated in the process of EMT." (PMID 27869227, 2016). "Although hypoxia can directly promote malignant progression, HIF-1α may interfere with cytotoxic tumor therapies by regulating autophagy under hypoxic conditions." (PMID 26867977, 2016). "Similarly to its effect in tumor cells, HIF1α mediates the metabolic switch from OXPHOS to aerobic glycolysis in lymphocytes and directly regulates the Th17/Treg balance in favor of Th17 cells." (PMID 27510264, 2016). "Many studies have shown that HIF-1α expression is increased in various tumors in humans including bladder, breast, and liver tumors, and compelling evidence indicates a strong correlation between elevated HIF-1α levels and tumor invasion, angiogenesis, and poor patient prognosis." (PMID 27658781, 2016). "We speculated that tumor inhibitory effect of ZnPP was partially due to decreasing HIF-1α expression through reducing HO-1 activity, and then consequently decreased tumor angiogenesis." (PMID 26822586, 2016).